NLRC5 (NLR family CARD domain containing 5)
Diseases named in the same sentence as NLRC5 in open-access papers (continued):
Sharing a sentence is not in itself a finding about the gene and the disease.
ischemic disease (1 paper, 2021). Lack of blood supply to an area of the body, resulting in impairment of tissue oxygenation. "Hence, the DD+NACHT domain of NLRC5 could be a druggable target for clinical therapy of ischemic disease states." (PMID 33754073, 2021).
Kawasaki disease (1 paper, 2019). A rare inflammatory disease characterized by an acute febrile, systemic, self-limiting, medium-vessel vasculitis primarily affecting children. "Compared with normal coronary arteries, NLRC5 expression was more abundant in VSMCs in both Kawasaki disease and coronary plaques; however, its expression was also ubiquitous, rather than localized in the proliferative medial layer." (PMID 31253783, 2019). "Therefore, we first examined the expression of NLRC5 in coronary arteries from patients with Kawasaki disease and in coronary plaques from patients undergoing coronary artery bypass graft surgery." (PMID 31253783, 2019).
lichen planus (1 paper, 2022). A chronic, recurrent, pruritic inflammatory disorder of unknown etiology that affects the skin and mucus membranes. "We also identified a SNP previously associated with lichen planus, an autoimmune condition that attacks cells of the skin and mucous membranes, that interacted with cortisol to influence the expression of NLRC5, a key regulator of adaptive immune responses." (PMID 36399508, 2022).
limb ischemia (1 paper, 2021). A ischemia that involves the limb. "We further investigated the role of NLRC5 in pathological angiogenesis using femoral artery ligation as a limb ischemia mouse model." (PMID 33754073, 2021).
lung carcinoma (1 paper, 2023). "Among these cell lines, A549 (lung carcinoma), MCF7 (mammary adenocarcinoma) and T47D (mammary ductal carcinoma) were selected for low NLRC5 expression and varying levels of HLA expression." (PMID 37108368, 2023).
lymph node metastasis (1 paper, 2024). "However, patients with higher NLRC5 expression had better prognosis, patients with higher age, HPV infection, lymph node metastasis, recurrence and histological grade had worse prognosis." (PMID 38961101, 2024).
lymphoid tumor (1 paper, 2013). "Future studies aimed at evaluating NLRC5 expression and mutations in a larger number of lymphoid tumor cells, and in primary tumors will contribute to delineate the potential importance of NLRC5 in tumor progression." (PMID 24319445, 2013). "Interestingly, the screening of a handful of lymphoid tumor cell lines suggested that NLRC5 is indeed expressed at low levels in several of these." (PMID 24319445, 2013).
mixed connective tissue disease (1 paper, 2020). Mixed connective tissue disease (MCTD) is a rare autoimmune disorder that is characterized by features commonly seen in three different connective tissue disorders: systemic lupus erythematosus, scleroderma, and polymyositis. "In line with the role of NLRC5 in immune response, the target CpGs of NLRC5 were enriched for CpGs that were previously associated with immune-related disorders (including auto-immune disorders primary Sjögren’s syndrome and mixed connective tissue disease and sTNFR2 levels)." (PMID 32859263, 2020).
Myocardial fibrosis (1 paper, 2019). "Therefore, down regulating the expression of NLRC5 may be useful to alleviate myocardial fibrosis." (PMID 31824312, 2019).
nasopharyngeal carcinoma (1 paper, 2024). A carcinoma arising from the nasopharyngeal epithelium. "Interestingly, Liu and colleagues observed NLRC5-mediated transactivation of endogenous BTN2A1 only upon EBV-reactivation, which also leads to IFNγ upregulation in nasopharyngeal carcinoma cells." (PMID 39035010, 2024).
osteoporosis (1 paper, 2022). A condition of reduced bone mass, with decreased cortical thickness and a decrease in the number and size of the trabeculae of cancellous bone (but normal chemical composition), resulting in increased fracture incidence. "In conclusion, this study revealed that the NF-κB signaling pathway, including the NF-κB1 RELA and NLRC5, may be implicated in alendronate's success in the treatment of osteoporosis, which can provide an early prediction of alendronate's efficacy in the treatment of osteoporosis." (PMID 35368772, 2022).
osteosarcoma (1 paper, 2025). A usually aggressive malignant bone-forming mesenchymal neoplasm, predominantly affecting adolescents and young adults. "Taken together, these data support consideration of PRC2-directed clinical studies, particularly when single-cell maps indicate H3K27me3-dominated inaccessibility at NLRC5/HLA regulatory elements, while recognizing that osteosarcoma-specific trial data are still limited." (PMID 41383594, 2025). "These concepts, supported predominantly by preclinical data and not yet validated in osteosarcoma-specific trials, align with single-cell chromatin evidence of reversible repression at HLA/NLRC5 regulatory elements and motivate biomarker-guided exploration in early-phase studies." (PMID 41383594, 2025).
ovarian endometriosis (1 paper, 2020). A non-neoplastic disorder characterized by the growth of endometrial tissue in the ovaries. "We hypothesizes that autophagy is implicated in NLRC5-mediated inflammation in ovarian endometriosis." (PMID 33013364, 2020). "Our results suggest that over-expression of NLRC5 promotes autophagy, thereby inhibiting inflammation in ovarian endometriosis." (PMID 33013364, 2020). "Our present findings demonstrate that inflammatory state in ectopic endometrium of ovarian endometriosis activates NLRC5." (PMID 33013364, 2020). "Furthermore, NLRC5 acts as an anti-inflammation regulator in ovarian endometriosis." (PMID 33013364, 2020). "In order to validate the assumption, we evaluate the effects of NLRC5 and autophagy in the inflammation of ectopic endometrial stromal cells (EESCs) of ovarian endometriosis patients, to specifically determine whether autophagy is involved in NLRC5-mediated inflammation in EESCs." (PMID 33013364, 2020). "This study may provide a possible explanation that if inflammation-activated NLRC5 was not sufficient, then ovarian endometriosis could grow rapidly via inhibiting autophagy." (PMID 33013364, 2020).
ovarian tumors (1 paper, 2023). "To investigate the cellular source of NLRC5 expression in human OC, we used a high-resolution scRNA-seq library consisting of 16 ovarian tumors." (PMID 38235131, 2023). "Furthermore, we found that NLRC5+ ovarian tumors respond better to PD-L1 blockade." (PMID 38235131, 2023).
postmenopausal osteoporosis (1 paper, 2022). Metabolic disorder associated with fractures of the femoral neck, vertebrae, and distal forearm. "The NF-κB1, RELA, and NLRC5 genetic variations affect the therapeutic response of alendronate treatment for postmenopausal osteoporosis." (PMID 35368772, 2022).
psoriasis (1 paper, 2018). An autoimmune condition characterized by red, well-delineated plaques with silvery scales that are usually on the extensor surfaces and scalp. "While all family members had CARD14 mutations, the PRP sufferers had an additional frame-shift mutation in DTX1, a regulator of regulatory T cells, while the psoriasis-affected individual harbored a mutation in NLRC5, a molecule that activates NF-κB but also regulates MHC-I transcription." (PMID 30386326, 2018).
Pulmonary Aspergillosis (1 paper, 2022). "On the contrary, CC homozygote of rs3806265 in NLRP3 and TT homozygote of rs1684579 in NLRC5 was associated with a high risk of aspergillosis, especially of IPA." (PMID 35407478, 2022). "A total of eight SNPs (NLRP3 rs3806265, NLRC4 rs212704 and NLRC5 rs1684579, rs12598522, rs3995817, rs3995818, rs34531240, rs28438857) were observed an association with susceptibility of pulmonary aspergillosis." (PMID 35407478, 2022). "The CC homozygote of NLRP3 rs3806265, TT homozygote of NLRC5 rs1684579 and T allele of NLRC5 rs12598522 were associated with a higher risk of aspergillosis while TT homozygote of NLRC4 rs212704 was associated with a lower risk of aspergillosis." (PMID 35407478, 2022). "So, it is reasonable that we found that the polymorphism of NLRC5 influenced the susceptibility to pulmonary aspergillosis, especially IPA." (PMID 35407478, 2022). "In our study, we found the TT homozygote of rs212704 in NLRC4 and C allele of rs12598522 in NLRC5 was associated with a lower risk of aspergillosis." (PMID 35407478, 2022). "For the NLRC4 rs212704, the TT homozygote was associated with a lower risk of aspergillosis (p = 0.0447; OR = 0.4468, 95%CI: 0.2071 to 0.959) while for the NLRC5 rs1684579 it was opposite (p = 0.0261; OR = 2.066, 95%CI: 1.085 to 4.018)." (PMID 35407478, 2022). "A total of 4 SNPs (NLRP3 rs3806265, NLRC4 rs212704, NLRC5 rs1684579, and rs12598522) were observed an association with aspergillosis risk." (PMID 35407478, 2022). "Our study demonstrated that the polymorphisms of NLRs (NLRP3, NLRC4, NLRC5) were associated with pulmonary aspergillosis risk, but there were still some limitations." (PMID 35407478, 2022). "Our results identified the association of NLRP3, NLRC4, and NLRC5 genetic variation with the susceptibility of pulmonary aspergillosis for the first time." (PMID 35407478, 2022). "Furthermore, the T allele of NLRC5 rs12598522 was more frequent in aspergillosis patients than healthy controls (p = 0.0305; OR = 1.601, 95%CI: 1.048 to 2.47)." (PMID 35407478, 2022). "The aim of this study was to investigate the relationship between NLRP3, NLRC4, and NLRC5 gene polymorphisms and susceptibility to pulmonary aspergillosis in non-neutropenic patients among the Chinese population." (PMID 35407478, 2022). "In this study, we investigated 16 SNPs in NLRP3, NLRC4, and NLRC5 genes among the southeastern Han Chinese population and analyzed the relationships between these SNPs and susceptibility of pulmonary aspergillosis in non-neutropenic patients." (PMID 35407478, 2022). "For the first time, we found rs3806265 in NLRP3, rs212704 in NLRC4 and rs12598522, rs34531240, rs28438857, rs3995818, rs3995817, rs1684579 in NLRC5 were associated with pulmonary aspergillosis in non-neutropenic patients." (PMID 35407478, 2022). "In an aspergillosis mouse model, several kinds of NLRs increased in the infected lungs, including NLRP3, NLRC4, and NLRC5, but their exact functions remain to be explored." (PMID 35407478, 2022).
Q fever (1 paper, 2014). A bacterial infection caused by Coxiella burnetii. "Most of the early genes were found to be up-regulated in monocytes from patients with acute Q fever, two of them, NLRC5 and RTP4, were up-regulated by IFN-γ, suggesting that IFN-γ plays a role in the host response during acute Q fever." (PMID 25346736, 2014).
renal cell carcinoma (1 paper, 2021). "NLRC5 could mediate proliferation, migration and invasion of renal cell carcinoma through wnt/beta-catenin signaling pathway." (PMID 34025929, 2021).
reovirus infection (1 paper, 2022). "A similar pattern of expression was for NLRC3 and NLRC5 in channel catfish (Ictalurus punctatus), in which the genes expression was induced significantly in liver by hemorrhage reovirus infection." (PMID 36119061, 2022).
retinal ischemia (1 paper, 2021). A ischemic disease that involves the retina. "In this study, we report a regulatory NOD-like receptor, NOD-, LRR- and CARD-containing 5 (NLRC5), as a key regulator on microglial pyroptosis and the retinal ischemia process." (PMID 34095138, 2021). "In the present study, we elucidate novel regulatory functions of NLRC5 in promoting microglial pyroptosis and ensuing RGCs death under retinal ischemia." (PMID 34095138, 2021).
Seizure (1 paper, 2021). A seizure is an intermittent abnormality of nervous system physiology characterized by a transient occurrence of signs and/or symptoms due to abnormal excessive or synchronous neuronal activity in the brain. "NLRC5 deficiency can reduce epileptic seizures caused by immune abnormalities in TMEV-infected mice, suggesting that NLRC5 can enhance the inflammatory response, regulate antiviral immunity, and promote the occurrence of epileptic seizures." (PMID 34220868, 2021). "Since NLRC5 can interact with other NLRs (such as NLRP3) and form inflammasomes, further study of the synergistic effect of NLRC5 and other inflammasomes on epileptic seizures is also necessary." (PMID 34220868, 2021).
squamous carcinoma (1 paper, 2024). "The chi-square test revealed a significant association of NLRC5 expression with the histological subtypes, where tumors with lower NLRC5 expression were more often squamous carcinoma subtype (p = 0.044)." (PMID 38961101, 2024).
vasculitis (1 paper, 2019). "The mean optical density of NLRC5 in glomeruli was significantly higher in crescentic class than non-crescentic class, and correlated with proteinuria level, Birmingham Vasculitis Activity Score and the proportion of crescents in the renal specimen." (PMID 31186034, 2019).
ZIKV infection (1 paper, 2019). "Activation of NOD1 and NLRC5 was observed following ZIKV infection." (PMID 30781519, 2019).
tumor (73 papers, 2013 to 2026). "Chi-square test showed that NLRC5 was a risk factor associated with tumor number, satellite nodule, and envelope invasion." (PMID 39132868, 2024). "It was found that the expression level of NLRC5 was significantly associated with tumor number (p = .005), satellite nodule (p = .018), and envelope invasion (p = .001)." (PMID 39132868, 2024). "Those tumours with loss of function in genes such as HLA-A, NLRC5 will lose the ability to present tumour neoantigens to dendritic cells or CD4 T cells." (PMID 36531162, 2022). "NLRC5 has recently been linked to the regulation of cancer immune evasion, but its role in tumor development is controversial." (PMID 33428330, 2021). "The increased tumor expression of NLRC5 is associated with better outcomes in human cancer and is a target of interest in anti-tumor immunity in transmissible tumors of another endangered species; the Tasmanian devil." (PMID 33717164, 2021). "NLRC5 was previously reported to be upregulated in ccRCC and positively associated with tumor progression." (PMID 32513235, 2020). "Taken together, these data underline the importance of NLRC5 in rising tumor immunogenicity and limiting tumor immune escape." (PMID 27437103, 2016). "In addition, significant reduction of SNAP23, VAMP7, and NLRC5 proteins indicates the reduction of cancer-associated protein trafficking, unconventional secretome, and tumor growth." (PMID 37941832, 2023). "In theory, the NLRC5-deficient mice could also aggravate tumor progression as NLRC5/CITA plays a crucial role in human cancer immunity through the recruitment and activation of tumor killing CD8+ T cells." (PMID 33754073, 2021). "Given its role in the transcription of MHC class I genes, it is reasonable to think that NLRC5 may play a prominent role in antitumor immunity and its loss may promote tumor immune evasion." (PMID 29408916, 2018). "Indeed, data reporting NLRC5 alterations are starting to emerge, showing that mutations and copy number variations are common across various tumor types." (PMID 27437103, 2016). "As such, NLRC5 mutation or silencing that results in downregulation of classical MHC class I in lymphoid malignancies could favor tumor development." (PMID 24319445, 2013). "However, low NLRC5 expression was associated with thicker Breslow thickness (p < 0.0001), higher Clark level (p = 0.0003), ulceration (p = 0.0003), advanced T stage (p = 0.0376) and more new tumor events after initial treatment (p = 0.0028)." (PMID 34307322, 2021). "Differential expression, survival analysis, immune infiltration estimation, and functional enrichment analyses were conducted to elucidate the role of NLRC5 in the tumor microenvironment." (PMID 41976340, 2026). "Second, writer effects diverge: METTL3 can promote antigen presentation via NLRC5 in tumor cells but is also required for DC co-stimulation—raising the practical challenge of cell-type–selective delivery or reader-focused strategies." (PMID 41280938, 2025). "Nucleophosmin 1 (NPM1), a nucleolar phosphoprotein, suppresses tumour immunogenicity by binding to IRF1 and preventing its association with the NLRC5 and CIITA promoters." (PMID 40673641, 2025). "The classifier established by the combination of NLRC5, tumor number, and envelope invasion were higher than that of just tumor number and envelope invasion." (PMID 39132868, 2024). "For example, NLRC5 was found to exert a significant role in anti-tumor immunotherapy by activating immunosurveillance in immunomicroenvironment." (PMID 38822039, 2024). "The results revealed a significantly higher expression of NLRC5 in tumor tissues as compared to non-tumor tissues." (PMID 39132868, 2024).